EGFR (epidermal growth factor receptor)
Diseases named in the same sentence as EGFR in open-access papers (continued):
Sharing a sentence is not in itself a finding about the gene and the disease.
esophageal cancer (continued). "And we also found that esophageal cancer cell line KYSE-510 with a low EGFR expression was hardly responsive to PT treatment." (PMID 30596104, 2018). "Given these, PT has a great potential to be a promising therapeutic candidate for treating EGFR+ esophageal cancers." (PMID 30596104, 2018). "Increasing studies have found various biologic markers in esophageal cancer, including epidermal growth factor receptor (EGFR), vascular endothelial growth factor (VEGF) and HER-2." (PMID 30477458, 2018). "Based on the preclinical findings of theliatinib, we propose that esophageal cancer patients with high EGFR levels (IHC H score ≥ 270) should potentially benefit from theliatinib treatment." (PMID 28881608, 2017). "YAP1 upregulates also EGFR expression is esophageal cancer cells, acting at the transcription level through binding to the EGFR promoter." (PMID 28930282, 2017). "Since SphK1 protein expression, measured by western blotting, has been found to correspond to EGFR phosphorylation in esophageal cancer cell lines, we also examined the relationship between SphK1 and pEGFR IHC staining." (PMID 28778177, 2017). "Even though K-Ras mutation in esophageal cancer is rare, upstream factors such as EGFR (epidermal growth factor receptor) are frequently over-expressed in esophageal cancer." (PMID 29207660, 2017). "The EGFR (epidermal growth factor receptor)-targeted drugs, gefitinib (Iressa) and erlotinib (Tarceva) were evaluated in esophageal cancer in phase II and phase III studies." (PMID 27172793, 2016). "Previous studies have reported modest treatment benefit of EGFR TKI in unselected esophageal cancer patients." (PMID 27013591, 2016). "Overexpression of YAP is associated with chemoresistance in esophageal cancer, and its interaction with the TEAD binding site in the EGFR promoter resulted in increased EGFR expression at the transcriptional level, causing resistance to 5-Fu and docetaxel." (PMID 27323827, 2016). "It has been demonstrated that overexpression of epidermal growth factor receptor (EGFR), which can be detected in 50%-70% of esophageal cancer cases, is correlated with poor prognosis." (PMID 26124180, 2015). "Inhibition of the YAP–TEAD interaction using verteporfin results in decreased EGFR expression and enhanced chemosensitivity to 5-fluorouracil and EGFR inhibitors in mouse xenografts of esophageal cancer." (PMID 26389076, 2015). "Nimotuzumab (h-R3) is an anti-EGFR antagonist humanized monoclonal antibody showing promising performance in head and neck cancer and esophageal cancer with excellent safety profile and limited side effect." (PMID 26124180, 2015). "It seemed apparent that the clinical benefit of the selective EGFR-TKI (gefitinib, erlotinib) or the EGFR-specific MoAB (cetuximab) were limited in esophageal cancer, with reported ORR of 2.0%-6.6% and PFS of 1.6-1.8 months." (PMID 26462025, 2015). "EGFR mutations (5–10%), amplification (20–30%), and overexpression (30–80%) in human esophageal SCC and AC have provided the rationale for targeting EGFR in esophageal cancer." (PMID 25593196, 2015). "Ec-LDP-Hr-AE inhibited esophageal cancer cell proliferation by regulating the activities of EGFR and HER2 signaling pathways." (PMID 24664246, 2014). "In esophageal cancer, EGFR overexpression occurs in 30%–90%, and HER2 overexpression ranges from 19%–43%." (PMID 24664246, 2014). "In this study, the antitumor activity of Ec-LDP-Hr-AE on esophageal cancer was investigated, because co-overexpresssion of EGFR and HER2 was observed in a majority of esophageal squamous carcinomas." (PMID 24664246, 2014). "A future study will investigate how the EGFR signaling pathway contributes to esophageal cancer progression or chemotherapy resistance in ESCC patients." (PMID 24131756, 2013). "This suggests that EGFR is a useful biomarker and provides a precise tool for prediction of survival of esophageal cancer patients." (PMID 24131756, 2013).
esophageal cancer (continued). "In esophageal cancer, EGFR overexpression by immunohistochemistry or gene amplification by fluorescent in situ hybridization (FISH) analysis occurs in 30-90% of tumors." (PMID 23232108, 2012). "This matches previous data indicating that between 8 and 30% of esophageal cancers have EGFR gene gain." (PMID 21274259, 2010). "In esophageal cancer, overexpression of EGFR by immunohistochemistry (IHC) is very common, occurring in approximately 80% of patients with adenocarcinoma and squamous cell carcinoma." (PMID 19636422, 2009). "Studies have experimentally confirmed that the impact of ac4C in esophageal cancer could influence the development and progression of the disease by targeting epidermal growth factor receptor (EGFR)." (PMID 39791162, 2025). "Nimotuzumab, an EGFR-targeted antibody, presented anti-tumor efficacy in esophageal cancer." (PMID 40672372, 2025). "A thorough examination of the current literature on EGFR and cancer prognosis highlights a consistent correlation between elevated EGFR levels and unfavorable patient outcomes across various cancer types, including head and neck, ovarian, cervical, bladder, and esophageal cancer." (PMID 39863836, 2025). "EGFR is emerging as an effective target for the treatment of esophageal cancer, and its overexpression may indicate poor survival." (PMID 40672372, 2025). "Additionally, as a humanized anti-EGFR monoclonal antibody, nimotuzumab has demonstrated promising safety profiles and potential therapeutic benefits in prior esophageal cancer studies." (PMID 38831450, 2024). "This suggests that EGFR-TKIs could be a promising treatment option for EGFR-positive esophageal cancer." (PMID 37251922, 2023). "However, most of these studies focused on the combination of EGFR-TKIs with chemotherapy in metastatic esophageal cancer patients, with limited research on LAEEC." (PMID 37251922, 2023). "Moreover, EGFR overexpression is closely related to tumor invasion, metastasis and chemoradiotherapy tolerance of esophageal cancer." (PMID 36467103, 2022). "Numerous EGFR monoclonal antibodies or EGFR tyrosine kinase inhibitors have been used alone or in combination with chemotherapy, radiotherapy or chemoradiotherapy to treat esophageal cancer, but the results have been disappointing." (PMID 36467103, 2022). "EGFR or HER2-targeted NIR-PIT has induced significant treatment effects in esophageal cancer cells." (PMID 35453596, 2022). "Both the epidermal growth factor receptor (EGFR) and insulin-like growth factor 1 receptor (IGF-1R) have been implicated in the development of cancers, and the increased expression of both receptors has been observed in esophageal cancer." (PMID 36142299, 2022). "Thus, dual-targeted NIR-PIT is a reasonable treatment for esophageal cancer patients with poor prognosis expressing both EGFR and FAP, as it can simultaneously attack both cancer cells and stroma and break the relationship." (PMID 36418422, 2022). "Thus, high expression of both FAP and EGFR strongly contributed to the prognosis of esophageal cancer." (PMID 36418422, 2022). "Copy number abnormalities of MET, CDK6 and EGFR were also observed in esophageal cancer tissues." (PMID 34944989, 2021). "As a new type of approach, targeted therapies have been confirmed to play an important role in the treatment of esophageal cancer; these include cetuximab and bevacizumab, which target epidermal growth factor receptor (EGFR) and vascular endothelial growth factor (VEGF), respectively." (PMID 33028804, 2020). "This positive feedback effect may be more significant in esophageal cancer with high EGFR expression." (PMID 32276266, 2020). "All the six human esophageal cancer cell lines presented EGFR expression." (PMID 32022229, 2020). "Furthermore, TEAD increases EGFR expression by directly binding to the EGFR promotor, which induces tumorigenesis and drug resistance in esophageal cancer." (PMID 31212916, 2019).
esophageal cancer (continued). "In the future, development of biomarkers, etc., may allow the usefulness of EGFR inhibitors to be demonstrated in particular subsets of subjects, but, at present, their usefulness in the treatment of esophageal cancer remains unknown." (PMID 30171414, 2019). "Additionally, YAP1 upregulates EGFR expression and increases cell proliferation and therapy resistance in esophageal cancer." (PMID 31601234, 2019). "Interestingly, PCLO has recently been shown to exert an oncogenic role in esophageal cancer by interfering with EGFR signalling." (PMID 31308377, 2019). "This implies that the surface densities of anti-EGFR antibody were not high compared to those of surface EGFR in esophageal cancer cell lines and association saturated in this study." (PMID 30104638, 2018). "A similar YAP1 upregulation of EGFR overexpression confers chemoresistance in esophageal cancer." (PMID 29435131, 2018). "Further studies may concentrate on the efficacy of CET in esophageal cancer patients with high-expressed EGFR." (PMID 30477458, 2018). "However, current established EGFR inhibitors such as mAbs have limited anticancer efficacy in EGFR-positive esophageal cancers, which create the need for better therapeutic avenue." (PMID 30596104, 2018). "EGFR has also been correlated with prognosis of esophageal cancer." (PMID 30477458, 2018). "As the cytotoxic mechanism of PT is markedly distinct from other EGFR-targeted agents, it may be a promising approach for EGFR+ esophageal cancer patients in the future." (PMID 30596104, 2018). "EGFR plays a key role in EMT induction in CD44+esophageal cancer cells though TGF-β." (PMID 28930282, 2017). "This cancer-targeted design of Se NPs provides a new strategy for synergistic treating of cancer with higher efficacy and reduced side effects, introducing GE11-Ori-Se NPs as a candidate for further evaluation as a chemotherapeutic agent for EGFR over-expressed esophageal cancers." (PMID 29019267, 2017). "We conducted a pre-clinical study to evaluate the anti-tumor activity of theliatinib in a panel of patient derived esophageal cancer xenograft (PDECX) models to determine the association between anti-tumor activity of theliatinib and different levels of EGFR expression in EC tumors." (PMID 28881608, 2017). "It is of interest to note that if one considers both gene mutations and gene amplifications, 48% of esophageal cancers have a genomic alteration in a pathway that can be pharmacologically targeted: this is the case for PI3KCCA, EGFR, ERBB2 and MET, just to mention the most frequently altered." (PMID 28930282, 2017). "Therefore, our data demonstrates that theliatinib would be clinically beneficial to esophageal cancer patients with high EGFR expression." (PMID 28881608, 2017). "Moreover, to date, no classification system has been implemented for assessment of EGFR or HER3 status in gastric or esophageal cancer." (PMID 26844548, 2016). "This suggests that EGFR amplification and overexpression rather than mutations drive esophageal cancers." (PMID 25593196, 2015). "An improved understanding of the importance of ADAM17 and the downstream EGFR signaling pathway in esophageal cancer invasion may aid in the development of therapeutic strategies aimed at reducing the invasiveness of esophageal cancer." (PMID 25351873, 2015). "EGFR overexpression has been reported previously in 40 to 84% of esophageal cancer tissues." (PMID 24131756, 2013). "In addition, IGFBP-3 has also been identified as a gene that is most highly up-regulated in EGFR-overexpressing esophageal cancer cell lines and primary esophageal tumors." (PMID 23232108, 2012). "One possible mechanism may be that the green tea polyphenols induce epidermal growth factor receptor inhibition in esophageal cancer cells." (PMID 17173682, 2006).
esophageal cancer (continued). "Additionally, a gold nanoprobe labeled with a heterobivalent (HB) peptide ligand, HB-Au-NPs, has demonstrated good results in esophageal cancer imaging, where it can specifically target overexpressed epidermal growth factor receptor (EGFR) and tyrosine kinase receptor 2 (ErbB2) in cancer cells." (PMID 38026877, 2023). "In recent years, many differential gene expression changes in esophageal cancer are related to the pathological mechanism, treatment, and prognosis of the disease; however, the treatment and prognosis improvement of esophageal cancer for known targets like EGFR and HER-2 are still insufficient." (PMID 34632074, 2021). "The depletion of EGFR might be other option in esophageal cancer treatments." (PMID 31354907, 2019). "Cetuximab (CET), a monoclonal antibody of EGFR, could improve outcomes when given in combination with chemotherapy/radiotherapy in several tumors, including advanced colorectal adenocarcinomas, squamous-cell head and neck cancer as well as esophageal cancer." (PMID 30477458, 2018). "However, EGFR-targeted antibodies have shown limited activity against esophageal cancer." (PMID 30596104, 2018). "In addition, the expression of EGFR has been related to the prognosis of esophageal cancer." (PMID 28415685, 2017). "Thus, anti-EGFR targeted therapy may have certain curative effect or generate breakthrough for esophageal cancer therapy." (PMID 29019267, 2017). "Thus, such treatment may extend to esophageal cancer patients with high EGFR expression and provide a survival benefit." (PMID 24131756, 2013). "Lastly, esophageal cancer often exhibits intrachromosomal amplification of MYC, ERBB2, EGFR, RB1, GATA4/6, CCND1, RTK and MDM2 as well as ecDNA-associated amplification of MYC and MDM2." (PMID 41415205, 2025). "In esophageal cancer, NAT10-mediated ac4C modification of tRNA boosts the translational efficiency of Epidermal Growth Factor Receptor (EGFR) mRNA." (PMID 40881352, 2025). "For example, siRNAs targeting VEGF, encapsulated in LNPs decorated with anti-EGFR antibodies, selectively silence VEGF expression in EGFR+ esophageal cancer, inhibiting angiogenesis and tumor growth while reducing off-target effects." (PMID 41030448, 2025). "Previous studies reported that in esophageal cancer cells, IGFBP-2 forms a nuclear complex with EGFR and DNA-PKcs following DNA damage." (PMID 38893232, 2024). "Current clinical trials, evaluate anti-MUC1 CAR T cells with PD-1 knockout in advanced esophageal cancer (NCT03706326) and anti-EGFR CAR T cells with TGFBR2 knockout in EGFR-positive solid tumors (NCT04976218)." (PMID 38962014, 2024). "MicroRNAs such as hsa-miR-27a-3p and hsa-miR-27b-3p were found to correlate with EGFR and PPAG in PAAD, and these 2 microRNAs were also correlated with gastric and esophageal cancers." (PMID 37857015, 2023). "To explore the expression of EGFR, HER2, and FAP in esophageal cancer, we conducted IHC using surgically resected tissues." (PMID 36418422, 2022). "The present study aimed to evaluate the anti-tumor efficacy of the epidermal growth factor receptor (EGFR)-targeting recombinant fusion protein Fv-LDP-D3 and its antibody-drug conjugate Fv-LDP-D3-AE against esophageal cancer." (PMID 35416106, 2022). "We demonstrated the relationship between EGFR/FAP expression and prognosis of patients with esophageal cancer and the stronger therapeutic effect of dual-targeted NIR-PIT than single-targeted NIR-PIT in experimental models." (PMID 36418422, 2022). "Immunoconjugates is the most prominent nanomedicine platform exploited for the active targeting PS delivery for esophageal cancer, with the anti-HER-2 and anti-EGFR antibodies being the most employed." (PMID 34834358, 2021).
esophageal cancer (continued). "LPCAT1 was highly expressed in esophageal cancer tissues and promoted esophageal cell invasion and migration via the SREBP-1/EGFR/PI3K signaling pathway." (PMID 34518524, 2021). "KSP-QRH-E3-IRDye800 were specific for human epithelial growth factor receptor 2 (HER2) and epidermal growth factor receptor (EGFR), which were have been found to be high-frequency gene amplified and overexpressed in early esophageal cancer." (PMID 34118882, 2021). "Cetuximab and trastuzumab are monoclonal antibodies of EGFR and HER2, respectively, which are overexpressed on many esophageal cancer cells." (PMID 34834358, 2021). "These antibody-based SERS NPs target and bind to the EGFR and HER2, overexpressed in the cancer cells, thereby facilitating the rapid detection and diagnosis of esophageal cancer." (PMID 34834358, 2021). "Depending on these results, we inferred that lncRNA LINC00152 down-regulation have anti-tumor effects via inhibiting EGFR/PI3K/AKT pathway and enhancing P21 expressions in esophageal cancer." (PMID 32190735, 2020). "Nimotuzumab is a humanized monoclonal antibody against epidermal growth factor receptor (EGFR), the efficacy of nimotuzumab added to nCRT for esophageal cancer is uncertain." (PMID 31258850, 2019). "EGFR, an extensively studied membrane-bound receptor tyrosine kinase (RTK), is commonly overexpressed in esophageal cancers." (PMID 30596104, 2018). "Results indicated that PT shows more effective antitumor activity as compared with Pan both on EGFR-overexpressed KYSE-450 and KYSE-150 esophageal cancer cells, especially on KYSE-450 cells." (PMID 30596104, 2018). "For example, most of the genes on the trunk of sample ESCC12 (CCND1, EGFR, APC, TGFBR2, XPC, XPA, FLI1, and NUMA1) have been identified and initially reported on the esophageal cancer." (PMID 30540749, 2018). "In esophageal cancer, YAP1 induces EGFR expression by binding to the TEAD binding site in the EGFR promoter." (PMID 29228705, 2017). "The two cell lines of the two main histotypes of esophageal cancer expressing divergent amounts of the two targeted receptors, EGF-receptor (EGFR) and HER2 emerge as an ideal model system to compare surface receptor-dependent toxin uptake and efficiency." (PMID 28128281, 2017). "As there are few relevant literature on the level of EGFR gene expression in ESCC, EGFR mRNA still cannot be an indicator of prognosis of esophageal cancer." (PMID 26099724, 2015). "In our series, 20 % of EC patients were EGFR FISH positive, representing a significant subgroup of patients with advanced esophageal cancer with potential upregulation of and growth dependency upon the EGFR pathway." (PMID 26478746, 2015). "It has been previously shown that EGFR signaling can directly activate STAT and mediate cell migration in esophageal cancer keratinocyte cells." (PMID 25686822, 2015). "For the KYSE150 cells, which express both EGFR and HER2, Ec-LDP-Hr-AE was the most cytotoxic to esophageal cancer cells when comparing with LDM and two monospecific fusion proteins (Ec-LDP-AE and LDP-Hr-AE)." (PMID 24664246, 2014). "This study was to evaluate antitumor activity of Ec-LDP-Hr-AE, a recently developed bispecific enediyne-energized fusion protein targeting both epidermal growth factor receptor (EGFR) and epidermal growth factor receptor 2 (HER2), on esophageal cancer." (PMID 24664246, 2014). "However, whether or not EGFR expression is associated with the survival of esophageal cancer patients remains controversial." (PMID 24131756, 2013). "Phase I and II clinical trials of the small-molecule TKIs of EGFR, erlotinib and gefitinib, in ESCC treatment are being carried out and modest activity has been observed in patients with esophageal cancers." (PMID 24103528, 2013).